LEP (leptin)
Diseases named in the same sentence as LEP in open-access papers (continued):
Sharing a sentence is not in itself a finding about the gene and the disease.
Obesity (continued). "In obesity, adipocytes secrete more leptin and less adiponectin, leading to the hypothesis that the LAR is a useful biomarker of adipocyte hypertrophy, insulin resistance, and cardiovascular risk." (PMID 38289144, 2024). "In individuals with obesity, leptin resistance and dysregulated ghrelin secretion may contribute to mood disturbances and increase the risk of depression." (PMID 38892598, 2024). "Thus, obesity is characterized by elevated leptin levels, which correlate with raised TSH, and decreased FT4 values, enhancing the susceptibility to thyroid autoimmunity and subsequent hypothyroidism." (PMID 39408957, 2024). "Although leptin administration reverses obesity in congenital leptin-deficient animals and humans, it does not affect diet-induced obesity." (PMID 38561362, 2024). "In the later stages of obesity, failure in NLRP3 inflammasome activation and M1 macrophage regulation is associated with the establishment of ovarian leptin resistance, which is associated with the disruption of ObRb-dependent (canonical) and ObRb-independent (noncanonical) signalling." (PMID 38580672, 2024). "Obesity of BBS is caused by defects in the neurological control of the appetite, although it is unclear whether defective leptin signaling or signaling by anorexigenic GPCR neuropeptide Y family receptors is the primary cause." (PMID 39126056, 2024). "Considering these results, the potential relationship between white tea and leptin may contribute to the management of obesity." (PMID 39768256, 2024). "In cases of obesity and abdominal obesity, leptin levels increase in the blood." (PMID 38297370, 2024). "Despite extensive research on obesity and metabolic syndrome, the relationship between dietary fat content, serum leptin levels, and inflammation markers, particularly in individuals with obesity with or at risk of metabolic syndrome, remains incompletely understood." (PMID 39700087, 2024). "Overweight and obesity in later life may lead to increased secretion of leptin hormone from adipose tissue, which could reduce deposition of amyloid-β (Aβ) in the brain, thereby lower the risk of cognitive impairment and AD." (PMID 39624409, 2024). "However, the metabolic imbalance in obesity cannot be corrected by high leptin, which results in the tissue of obese patients becoming less sensitive to leptin, triggering “leptin resistance”." (PMID 39139641, 2024). "This decreased Ob-Rb expression could be due to the leptin excess and the low-grade inflammation present in obesity." (PMID 39062791, 2024). "Other studies suggest that leptin resistance is a key factor in the development of obesity." (PMID 39684379, 2024). "Leptin is an obesity-related hormone that plays an important role in breast cancer progression." (PMID 38791252, 2024). "This disruption contributes to overeating, leptin and insulin resistance, and the onset of obesity." (PMID 38892653, 2024). "This implies that in cases of obesity, leptin’s altered control of the SNS could significantly impact ovarian function and contribute to conditions like PCOS." (PMID 39963180, 2024). "These elevated CNS leptin levels may subsequently induce IL‐6 production in CNS, resulting in increased CSF IL‐6 levels secondary to overweight/obesity." (PMID 39401137, 2024). "In individuals with obesity, the levels of inflammatory adipokines such as leptin, adiponectin, interleukin-6 (IL-6), heparin-binding epidermal growth factor-like growth factor (HB-EGF), and vascular endothelial growth factor (VEGF), which are secreted by adipose tissue, are elevated." (PMID 39524226, 2024). "On the other hand, previous studies have associated serum leptin with an increased risk of insulin resistance in children and MetS in adults, independent of obesity status." (PMID 38668349, 2024). "In the context of obesity, alterations in sexual dimorphism are observed in response to leptin." (PMID 38397015, 2024).
Obesity (continued). "In addition to direct targeting of relevant appetite-regulating nuclei in the brain, restoring sensitivity to the adipose secreted hormone leptin is also of interest in the treatment of obesity." (PMID 39183855, 2024). "However, an effective method of treating obesity with leptin has been described, which is somewhat the opposite of administering this hormone." (PMID 39057043, 2024). "While leptin, an adipocyte-derived hormone/cytokine that primarily regulates food intake and basal metabolism, is crucial for glucose uptake in effector T cells, chronic systemic leptin secretion in obesity can disrupt CD4+ T cell differentiation and lead to poor T cell responses." (PMID 39469362, 2024). "Therefore, it is crucial to prevent the development of leptin resistance during puberty in children with obesity." (PMID 40302954, 2024). "Obesity affects the balance of the HPO axis primarily by increasing leptin levels." (PMID 39630623, 2024). "This review seeks to offer a comprehensive examination of the influence of leptin resistance on hippocampal function, with particular emphasis on the mechanisms affecting glutamatergic transmission and synaptic plasticity in the context of obesity." (PMID 39594988, 2024). "Leptin also appears to be an upstream regulator in the obesity-breast cancer axis." (PMID 39439572, 2024). "A literature search was performed using the PubMed and Cochrane databases to identify studies related to obesity and EOCRC, with keywords including ‘EOCRC’, ‘obesity’, ‘obesity-related hormones’, ‘itaconate’, ‘adiponectin’, ‘leptin’, ‘M2a macrophage’, and ‘microbiome’." (PMID 38611081, 2024). "Obesity-induced neuroinflammation was first described in the hypothalamus, evidenced by the upregulation of JNK and NF-kB signaling and a reduced insulin and leptin profile caused by exposure to a high fat diet (HFD)." (PMID 38598021, 2024). "Thus, the anorexigenic action of TriMetChalc in the ob/ob mice is of interest in the perspective of the future development of TriMetChalc as an anti-obesity drug, since human obesity is characterized by leptin resistance." (PMID 39337328, 2024). "The state of obesity is marked by a high ratio of leptin to adiponectin." (PMID 39432545, 2024). "We further analyzed the secretion patterns of 105 different cytokines and chemokines by THP-1 monocytes in response to 24 h incubation with OSAS and obesity related parameters hypoxia, tumor necrosis factor α (TNFα) and leptin using membrane based human cytokine arrays." (PMID 38172514, 2024). "Furthermore, biological responses to the adipocyte-produced hormone leptin, which is integral in appetite regulation and control of breathing, are altered in obesity, leading to leptin resistance." (PMID 38338762, 2024). "In contrast, central BDNF knockdown leads to obesity and elevated leptin expression in adipocyte." (PMID 39655343, 2024). "For instance, adipose tissue in obesity generates and releases an increased amount of pro-inflammatory adipokines, including tumor necrosis factor- alpha (TNF-α), interleukin-6 (IL-6), and leptin, which results in skin inflammation and is associated with psoriasis." (PMID 38550599, 2024). "Increasing numbers of M1 macrophages as well as activated adipocytes present in inflamed fat tissue produce TNF-α, IL-6 and other inflammatory mediators including leptin and resistin that promote the occurrence of cardio-metabolic syndrome and hypertension in obesity." (PMID 38541059, 2024). "Taken together, the kidney might be both involved in leptin metabolism, as well as a target for the detrimental effects of leptin in obesity." (PMID 38627329, 2024). "These molecules play crucial roles in metabolic regulation, inflammation, and tissue remodeling, contributing to the complex interplay observed in obesity-related pathology, i.e., leptin is crucial in promoting the esterification of fatty acids (FA) into triglycerides (TG) while enhancing lipolysis." (PMID 39061837, 2024).
Obesity (continued). "Rodents with obesity displayed elevated circulating leptin concentrations." (PMID 38933275, 2024). "This study revealed that the AG genotypes of the leptin (LEP) A-2548G polymorphism and the AA genotypes of the fat-mass and obesity-associated protein (FTO) rs9939609 polymorphism were associated with a higher risk of obesity." (PMID 39766314, 2024). "The leptin secreted by adipose tissue induced by obesity may serve as a bone growth factor for patients with growth hormone deficiency, playing a role in maintaining growth velocity." (PMID 38828392, 2024). "Over the past dozen years, research has indicated that CEL may serve as a leptin sensitizer, leading to decreased body weight and showing promise as a potential pharmacological treatment for obesity." (PMID 39161898, 2024). "Four CVRPs were positively associated with obesity irrespective of age, leptin, IL-1Ra, IL-18 Ra, and MIP-1a, and all four were upregulated in PCOS." (PMID 39858399, 2024). "In addition, the inhibitor of cytokine signaling 3 (SOCS3) and/or protein tyrosine phosphatase 1B (PTP1B) appear to share the suppressive effects on insulin and leptin signalings that are frequently observed in obesity." (PMID 38921683, 2024). "Obesity may also contribute to airway vascular remodeling, influenced by factors such as VEGF, the role of leptin, deficiency in adiponectin, and angiopoietin." (PMID 38562155, 2024). "A German study found that children with obesity showed higher growth at birth than their normal-weight counterparts and had an accelerated growth rate thereafter, which was associated with increased levels of IGF-1, insulin, and leptin in these children." (PMID 38398863, 2024). "It thoroughly examines current research on regulating energy balance in companion animals, emphasizing the clinical application of various peptides, including ghrelin, phoenixin (PNX), asprosin, glucagon-like peptide 1 (GLP-1), leptin, and nesfatin-1, in veterinary obesity management." (PMID 39057043, 2024). "Obesity may elevate leptin levels and reduce adiponectin levels, which has been demonstrated to enhance osteoclast activity and result in bone loss." (PMID 39744530, 2024). "Obesity and hypertension share common pathophysiological mechanisms, such as overactivity of the renin–angiotensin–aldosterone and the sympathetic nervous systems, insulin resistance, and disruption of the leptin pathway." (PMID 39457606, 2024). "Obesity-induced increases in leptin levels may contribute to heightened inflammation and more severe symptoms through its interaction with interleukin-1 β (IL-1β)." (PMID 38790590, 2024). "Obesity might lead to diabetes mellitus and depression through reduced adiponectin and increased leptin and resistin." (PMID 37927197, 2024). "Leptin resistance and inflammation demonstrated by higher plasma and central nervous system levels of interleukin-6 (IL-6), IL-1β and tumour necrosis factor-α, are mechanisms connecting obesity and diabetes with AD." (PMID 38290839, 2024). "WAT from individuals with obesity increases leptin secretion, leading to leptin resistance by desensitizing its receptors in the hypothalamus, prejudicing its regulation of food intake and contributing to obesity." (PMID 38612973, 2024). "Thus, leptin resistance appears to be present in most cases of obesity, perhaps analogous to insulin resistance in type 2 diabetes." (PMID 38165042, 2024). "A clinical trial (NCT05494112) is currently underway to evaluate the efficacy of Celastrol in treating obesity by restoring leptin sensitivity, which may have important implications for neurodegenerative diseases in the future." (PMID 39594988, 2024). "Future studies are required to address whether or how ADGRL1 function is regulated by glucose, insulin, leptin, and different diets in widely used mouse models of the metabolic syndrome such as db/db, ob/ob and diet-induced obesity models." (PMID 37712955, 2024).
Obesity (continued). "These miRNAs showed a strong correlation with various obesity markers, including body mass index (BMI), waist/hip ratio (WHtR), adipokines, adiponectin, leptin and fasting blood sugar levels (FBS), insulin, HOMA-IR, triglycerides (TG), HDL-C, C-peptide and LDL-cholesterol." (PMID 38541185, 2024). "In addition, OSAS and obesity related plasma levels of adiponectin, leptin, lipocalin, and matrix metallopeptidase 9 (MMP-9) were correlated with monocyte subset measurements and clinical characteristics to explicitly distinguish these two conditions." (PMID 38172514, 2024). "TSH variations due to increasing leptin, ANGPTL8, and TyG index may enhance the risk of insulin resistance diseases, such as obesity and CVD, in Saudi females with T2DM." (PMID 39252284, 2024). "Consistent with classic endocrine logic, leptin replacement reverses obesity due to leptin mutations but does not correct obesity caused by mutations in its receptor." (PMID 38165042, 2024). "We crossed Gpr75–/– mice with Lepob-mutant mice to determine whether GPR75 is involved in leptin signaling and whether loss of GPR75 would attenuate the obesity phenotype of Lepob-mutant mice." (PMID 39137039, 2024). "Previous studies have shown that not only obesity but also diet could positively or negatively influence leptin secretion." (PMID 38668349, 2024). "Through the observation of a genetic mouse model of obesity and diabetes (db/db mouse), he found that impaired leptin signaling has harmful effects on the regulation of sleep volume, sleep structure and time consolidation of wake states, leading to a decrease in circadian rhythms of activity." (PMID 39839286, 2024). "Leptin resistance represents a primary pathological manifestation in obesity." (PMID 38623207, 2024). "In addition to hepatic diseases, the concept of circadian dysfunctionsinducing obesity and leptin resistance were demonstrated by the sameresearch team in the previous year." (PMID 39072055, 2024). "Excessive leptin secretion or reduced adiponectin production by adipocytes in obesity may also directly affect bone formation or indirectly affect bone resorption." (PMID 39124655, 2024). "It is also intriguing whether the WD- or choline-dependent changes observed in leptin levels in late gestation may affect foetal programming of obesity." (PMID 38762543, 2024). "Hormones in breast milk, such as leptin, adiponectin, and ghrelin, may influence long-term appetite signaling and have a preventive effect on the development of obesity." (PMID 39459341, 2024). "However, patients with obesity have limited leptin permeability across the blood-brain barrier due to transporter receptor resistance and impaired LEPRb signaling, which then attenuates the pro-respiratory effects of the hormone." (PMID 38553569, 2024). "It remains unclear whether elevated leptin levels are actively involved in the development of obesity or are markers of metabolic dysfunction due to chronic overnutrition." (PMID 38892118, 2024). "That adipose leptin production is increased in obese individuals, has led to the hypothesis of obesity-induced leptin resistance." (PMID 39065709, 2024). "Leptin, plasminogen activator inhibitor 1 (PAI1), and alpha-1 acid glycoprotein 1 (AGP1) are associated with obesity and may be used as biomarkers." (PMID 39408963, 2024). "Additionally, since individuals with elevated plasma leptin are often obese, it is challenging to isolate the effects of hyperleptinemia from other obesity-related adverse influences on cardiac structure and function." (PMID 39612121, 2024). "IPA acts as an endogenous leptin sensitiser to counteract obesity." (PMID 39606796, 2024). "The mechanisms of the protective effects of E2 against obesity are still being elucidated, but they may involve regulation of glucose-insulin homeostasis and leptin, affecting food intake and energy expenditure." (PMID 38883397, 2024).
Obesity (continued). "However, excessive leptin secretion resulting from obesity can induce leptin resistance in the hypothalamus, consequently suppressing GnRH release and inhibiting testosterone secretion." (PMID 38978622, 2024). "Therefore, obesity leads to dramatic changes in ovarian leptin signalling, with repercussions for folliculogenesis and ovarian function in general." (PMID 38580672, 2024). "However, contradictory evidence suggests potential cardioprotective roles of leptin in specific subgroups, highlighting the complexity of leptin resistance and sensitivity influenced by factors like sex, ethnicity, and obesity status." (PMID 39682585, 2024). "Leptin expression and circulating levels increase and reflect the degree of adiposity in diet-induced obese and several mouse obesity models, but hyperleptinemia clearly doesn’t prevent obesity." (PMID 38165042, 2024). "In obese individuals, hyperleptinemia is insufficient for preventing the dysregulation of energy balance, suggesting that individuals with obesity may exhibit leptin resistance." (PMID 38397015, 2024). "Leptin dysregulation in the setting of obesity might interfere with gonadotropin-releasing hormone (GnRH) release, which can impact the generation of reproductive hormones and possibly result in infertility." (PMID 39595164, 2024). "Moreover, the results indicated that high fat consumption (SFAs) increased IL-6 and leptin levels in participants with obesity." (PMID 39700087, 2024). "Moreover, higher LEP levels were also presented in these obese individuals with a higher percentage of body fat, which was mainly mediated by typical LEP resistance in obesity." (PMID 38668364, 2024). "It was also observed that weight loss did not occur with the treatment of exogenous leptin in obesity, indicating resistance to the effects of leptin." (PMID 38807723, 2024). "Interestingly, HDAC6 inhibition in db/db and obese mice increases leptin sensitivity and decreases obesity." (PMID 39109269, 2024). "Furthermore, leptin’s angiogenic and atherogenic effects have led to its recognition as an essential marker in obesity, diabetes, and CVD." (PMID 39335642, 2024). "Moreover, the progression of inflammation, oxidative stress, and heightened leptin levels in obesity is strongly correlated with the development of CVD and hypertension." (PMID 38397015, 2024). "Moreover, within the AD patient population, individuals with obesity demonstrated higher serum leptin levels than those of standard weight." (PMID 38263019, 2024). "Obesity typically increases circulating leptin levels, but the effects of leptin may be decreased due to developing leptin resistance." (PMID 38999854, 2024). "Abdominal obesity is considered to be an inflammatory state, and many inflammatory factors come from visceral adipose tissue, such as IL-6, TNF-α, C-reactive protein (CRP), leptin, etc., which may lead to obesity-related airway inflammation." (PMID 38926790, 2024). "In rodent models and humans, obesity-induced leptin resistance in the hippocampus has significant implications for executive functions, including decision-making, impulse control and attention regulation, which are vital for maintaining cognitive control over food intake." (PMID 39594988, 2024). "Also, obesity-induced chronic inflammation and disruptions of insulin and leptin signaling can result a disproportionate or hyper-inflammatory response, which, together with elevated ferritin levels, can be a direct cause for ARDS and cytokine storm." (PMID 38822415, 2024). "Although leptin is recognized for its ability to regulate appetite and metabolic rate, it also has proinflammatory and atherogenic effects that intensify the inflammatory environment in obesity." (PMID 39767248, 2024). "Considering that the typical phenomena leading to obesity are increased fat mass, adipocyte hypertrophy, and a decreased response to leptin, it can be hypothesized that obesity was initiated by chronic noise stress." (PMID 39456767, 2024).